UCA1 (urothelial cancer associated 1)
Diseases named in the same sentence as UCA1 in open-access papers (continued):
Sharing a sentence is not in itself a finding about the gene and the disease.
tumor (continued). "More specifically, 4 lncRNAs (CCAT1, CCAT2, HOTAIR, and UCA1) were upregulated, while 2 lncRNAs (MALAT1 and TUG1) and 1 circRNA (CDR1AS) were downregulated in CRC tumor tissues compared to NATs." (PMID 30195762, 2018). "In vivo study showed that UCA1 knockdown and NR2C2-uORF overexpression combined with silenced NR2C2 produced a tumor of the smallest volume and resulted in the longest survival time in nude mice." (PMID 30518750, 2018). "In vivo studies further confirmed that UCA1 knockdown combined with uORF overexpression and NR2C2 silenced suppressed tumor growth greatly and led to the longest survival in a xenograft mouse model." (PMID 30518750, 2018). "Either high expression of HOTTIP, LINC00152, LINC00673, MALAT1 and UCA1, or low expression of AC007392.4, MEG3 and NKILA is found in tumor tissues." (PMID 29416703, 2018). "Remarkably, lnc-UCA1 knockdown combined with uORF overepression and NR2C2 knockdown led to severe tumor suppression in vivo." (PMID 30518750, 2018). "We confirmed the upregulation of UCA1 in HSCC by assessing its expression levels in a cohort of 53 patient tumors and paired non-tumor samples." (PMID 28327194, 2017). "Oncogenic activity of UCA1 in CRC was the result of its decoy function for miR-204-5p, a critical tumor-suppressive miRNA." (PMID 29147648, 2017). "UCA1 is expressed at a dramatically higher level in TSCC tumor tissues than in neighboring non-tumor tissues, and patients with LNM express much higher levels of UCA1." (PMID 27802187, 2017). "To explore the contribution of the downstream signaling pathway of UCA1 to the tumor suppressor function of ATR, we identified the potential sponge function of UCA1 on miRNAs." (PMID 28209917, 2017). "Expression of the seven lncRNAs UCA1, MALAT1, H19, GAS5, TUG1, ncRAN (SNHG16) and linc-UBC1 (BLACAT) was measured by RT-qPCR in UC tissue set 1 consisting of 106 tumor tissues and 10 benign tissues obtained from radical cystectomies." (PMID 28430799, 2017). "The results also suggested that lenti-UCA1-siRNA stably-transfected BGC-823 cells significantly inhibited p-AKT3 and p-mTOR protein expression in isolated tumor tissues of these animals." (PMID 29212166, 2017). "The univariate Cox regression analyses of overall survival demonstrated that tumor stage (P = 0.020), TNM stage (P = 0.011), postoperative recurrence (P=0.021) and UCA1 expression (P = 0.001) were all good prognostic predictors." (PMID 29221199, 2017). "The average tumor weight and tumor volume were markedly higher in the NCI-N87/UCA1 group than in the NCI-N87/NC group (**P<0.01)." (PMID 28569779, 2017). "The results manifested that UCA1 knockdown or CDDP treatment notably impeded the tumor growth, exhibited as declined tumor volume and decreased tumor weight." (PMID 29125238, 2017). "Taken together, our findings for the first time identify the role of UCA1 as a tumor promoter and a pro-metastatic factor in HSCC, demonstrating that UCA1 is a potential prognostic biomarker and therapeutic target in HSCC." (PMID 28327194, 2017). "UCA1 is highly expressed in CRC and is involved in tumor cell proliferation, apoptosis and cell cycle progression of tumor and the prognosis of CRC patients." (PMID 28108736, 2017). "Rescue experiments suggested that downregulation of miR‐184 partly reversed the tumor suppression effect and CDDP chemosensitivity of UCA1 knockdown in CDDP‐resistant OSCC cells." (PMID 29125238, 2017). "Noticeably, higher UCA1 expression in CRC was significantly correlated with a larger tumor size (P = 0.010), greater tumor depth (P = 0.041) and lymphatic invasion (P = 0.035)." (PMID 27046651, 2016). "Next, qRT-PCR analysis of UCA1 expression and immunostaining analysis of proliferating cell nuclear antigen (PCNA) protein expression were performed in resected tumor tissues." (PMID 25760077, 2015).
tumor (continued). "According to recent data, UCA1, a lncRNA with oncogenic role in ESCC, is an independent predictor of shorter OS and is related to advanced tumor stage and differentiation grade, increased lymphatic invasion as well as poor survival rates." (PMID 26064090, 2015). "UCA1, exhibits high expression in CRC tissues and correlates with larger tumor size and unfavorable prognosis of the CRC patients." (PMID 26064090, 2015). "FAM171A2 transcripts showed strong negative correlations with the tumor-suppressor miR-15/16 family and with tumor-promoting lncRNAs such as UCA1 and PVT1." (PMID 41303609, 2025). "Other lncRNAs showed directional changes consistent with tumor-promoting activity but did not independently predict disease category when adjusted for age and UCA1." (PMID 41226033, 2025). "In addition, fetal-I tumor organoids (hepatic-intermediate) expressed markers related to tumor progression and invasion, including TSPAN8, CKB, UCA1, and FXYD3." (PMID 39567475, 2024). "Their research revealed that UCA1 upregulates several tumour‐promoting genes such as CAMP responsive element‐binding protein 1 (CREB1), B‐cell lymphoma 2 (BCL2) and Ras‐related protein Rab‐22A (RAB22A) by sponging miR‐204‐5p, which is a tumour suppressor." (PMID 38506091, 2024). "Mechanistically, UCA1 could increase the expression of MMP14 through sponging miR-485-5p, thereby promoting tumor metastasis." (PMID 38725621, 2024). "This conflicting finding might be explained by the fact that UCA1 was cherished by CRC cells, which impelled the preservation of this lncRNA by tumor cells by reducing its release through exosomes." (PMID 35663957, 2022). "Studies have found that UCA1 also promotes the expression of HXK2 by interacting with miR-203, thereby facilitating the aerobic glycolysis of tumor tissues and enhancing the Warburg effect to promote tumor cell proliferation and metastasis." (PMID 35241975, 2022). "We found significant correlations were found between tumor stage and two lncRNAs (MKLN1-AS and UCA1), which indicated the level of two lncRNAs could reflect the cancer severity and play a role in the prognostic value for BC." (PMID 36119544, 2022). "However, UCA1 is also positively correlated with Gleason score, advanced TNM (tumour/node/metastasis) stage and shorter overall survival of PCa patients." (PMID 35159022, 2022). "Silencing UCA1 or up-regulating miR-122-5p degraded SOX2 expression, and reduced invasion, migration and proliferation of CD133+CaSki cells while advanced apoptosis and suppressed the tumor volume and weight in nude mice." (PMID 34053467, 2021). "Moreover, some of the key signaling pathways for tumor progression, including the Wnt/β-catenin, PI3K/AKT, MAPK, and notch signaling pathways, were suppressed following UCA1 knockdown." (PMID 34322395, 2021). "Many studies have revealed that lncRNAs, such as lncRNA ARSR, lncRNA UCA1, and lncRNA TUC339, are the important RNA cargoes of tumor exosomes, and these lncRNAs mediate the role of exosomes in regulating drug resistance, tumor growth, and macrophage activation in many cancers." (PMID 33495437, 2021). "Furthermore, we found that the high expression of UCA1 is positively correlated with serum AFP, tumor size, and distant metastasis, and predicts poor prognosis." (PMID 33565716, 2021). "UCA1 is involved in the regulation of the PI3K/AKT, Wnt/β-catenin, MAPK, NF-κB and JAK/STAT signaling pathways, affecting a series of cellular biological functions, such as cell proliferation, apoptosis, migration, invasion and tumor drug resistance." (PMID 33777227, 2021). "Therefore, it is feasible to use either LncRNA UCA1 si treatment and/or ROCK inhibitor to limit tumor cell migration and invasion and to reduce HA/CD44-induced tumor metastasis and progression." (PMID 31293964, 2019). "The tumor weight of the isolated tumors in the UCA1 group was significantly increased when compared to negative control group." (PMID 31596734, 2019).
tumor (continued). "The tumor volume was measured every 5 days for up to 30 days, and U87 cells with UCA1 overexpression showed significantly larger volume of tumor in the nude mice than that in the negative control group." (PMID 31596734, 2019). "Besides, lncRNAs, as an important tumor regulator, has been widely concerned due to its potential role in tumor development, progression, and metastasis, such as TUG-1, UCA-1, MALAT1 and so on." (PMID 31844718, 2019). "UCA1 is probably not a strong general prognostic marker for CRC as its overexpression is dependent on the primary tumor site (colon vs. rectal) and molecular characteristics, such as the microsatellite stability profile." (PMID 30441811, 2018). "Following this second hypothesis, we computationally found reliable interactions between UCA1 and the 3′-UTRs of ANLN, BIRC5, IPO7, KIF2A, and KIF23 that overlapped several miRNA-binding sites of tumor-suppressor miRNAs." (PMID 30195762, 2018). "In our previous study, we elucidated that UCA1 expressions are significantly increased in CRC tissues and cells, and this high UCA1 expression level is significantly correlated with larger tumor size, greater tumor depth and less differentiated histology." (PMID 30377411, 2018). "Although no obvious nodes were found in the lung tissues from the UCA1 overexpression groups, metastatic tumor cells were observed in the HE-stained pulmonary tissue slides." (PMID 30464170, 2018). "Knockdown of LINC00673, MALAT1 and UCA1, and overexpression of MEG3 and NKILA can inhibit tumor progression, which might become prospective treatment methods." (PMID 29416703, 2018). "First, the UCA1 expression in tumor tissues and its matched nontumor tissues of 39 patients with GC was measured by real-time RT-PCR." (PMID 28569779, 2017). "We found that UCA1 expression level was significantly higher in tumor tissues than that in nontumor tissues." (PMID 28569779, 2017). "To confirm that UCA1 is upregulated in HSCC tumor tissues, we performed qRT-PCR to measure the relative expression levels of UCA1 in 53 pairs of HSCC tumor tissues and their corresponding adjacent non-tumor mucosae." (PMID 28327194, 2017). "Among the 39 GC tissues, 69.2% (27/39) of the tumor samples showed upregulation of UCA1 compared with the matched nontumor tissues (relative expression ratio <1.0, P<0.01)." (PMID 28569779, 2017). "Compared with negative control group, knockdown of UCA1 or HBx significantly suppressed tumour growth." (PMID 27009634, 2016). "We injected Hep3B cells without/with either knockdown of UCA1, HBx alone or simultaneous silence of UCA1 and HBx together into nude mice, and monitored the tumour growth rate and tumour size." (PMID 27009634, 2016). "Taken together, these data illustrated above suggested that part of the disregulated lncRNAs such as up-regulated AFAP1-AS1, UCA1 and down-regulated ENSG00000218510 could predict poor prognosis and might contribute to tumor progression in PDAC." (PMID 27628540, 2016). "The expression of p27 was at lower level in 54.8% tumour tissues as compared to the non-tumour tissues (17/31), and a significantly inverse correlation was observed between UCA1 and p27 levels (R2 = 0.1126, P = 0.015, Wilcoxon’s signed-rank test)." (PMID 27009634, 2016). "To evaluate the correlation between UCA1 and p27, we measured the mRNA levels of p27 and UCA1 in 31 paired tumour and adjacent nontumor tissues by real-time PCR." (PMID 27009634, 2016). "HOTAIR, MALAT1, HULC, and UCA1 were similarly expressed between tumor tissues and nontumor tissues in HCC patients (P = 0.448, 0.138, 0.085, and 0.373, resp)." (PMID 26136615, 2015). "Furthermore, the knockdown of UCA1 in gastric cancer cells enhanced cisplatin-induced apoptosis, possibly through its reduced ability to recruit EZH2 and to activate the PI3K/AKT signaling pathway, which is involved in tumor progression." (PMID 38256203, 2024).
tumor (continued). "claimed that depletion of UCA1 curbed malignant progression of MM by up-regulating miR-331-3p abundance and reducing the abundance of IL6R, suggesting that miR-331-3p might function as a tumor suppressor and thus hinder the malignant phenotypes of tumor." (PMID 37173768, 2023). "Moreover, we demonstrated that silencing UCA1 or up-regulating miR-122-5p would reduce SOX2 expression and depress the invasion, proliferation, migration, boost apoptosis of CD133+CaSki cells as well as suppress the tumor weight and volume in nude mice." (PMID 34053467, 2021). "UCKL1-AS1, LOC146880, UCA1, C3P1, LINC00261, and LINC01018 may be important in the progression of HCC and their expressions were detected in 20 patients with newly diagnosed HCC and their paired non-tumor liver tissue samples." (PMID 32201648, 2020). "To confirm this result, we detected UCA1 expression in tumor tissues and their matched nontumor tissues of 30 patients with GC by qRT-PCR and found that UCA1 expression level was significantly higher in tumor tissues than that in nontumor tissues." (PMID 32328192, 2020). "Invalidating an lncRNA, like UCA1 in CRC, may have the advantage of both inhibiting epigenetic silencing through chromatin remodeling for several tumor suppressor genes and stimulating the miRNA-mediated mRNA degradation of oncogenes due to a decreased ceRNA level." (PMID 30441811, 2018). "Similarly, UCA1 expression tended to be higher in non-invasive and in low-grade tumours rather than muscle-invasive tumours of set 1, but these differences were not statistically significant." (PMID 28430799, 2017). "Moreover, UCA1 promoted GBC cell proliferation and metastasis in vitro and tumor growth in vivo." (PMID 28624787, 2017). "UCA1 depletion could suppress cell proliferation, colony formation, migration and invasion and induce G0/G1 cell cycle arrest in HCC cell lines in vitro, as well as inhibit tumor growth in vivo." (PMID 25760077, 2015). "Conversely, the result of the UCA1 test did not vary significantly between low-grade and high-grade tumours (60.9 vs. 71.4%) and did not correlate with stage (57.1% for pTa tumours vs. 93.3% for pT1 tumours; 59.1% for ≥pT2 tumours)." (PMID 26191476, 2015). "We further characterized whether or not UCA1 affected tumor growth in vivo." (PMID 29516678, 2018). "The nucleotide supplementation experiments fully demonstrated that UCA1 affected the metabolites IMP, GMP, and GTP levels simultaneously and that GTP supplementation alone did not reverse the tumor cell phenotype." (PMID 37215997, 2023). "But they did not found any significant correlation between UCA1 expression and serum AFP level or tumor size." (PMID 33565716, 2021). "Compared to non-tumor tissues, NSCLC tissues exhibited significant higher expression levels of UCA1 in non-cancer tissues (p < 0.05)." (PMID 33514344, 2021). "Overall, the results indicate that motif 3 (UCA1/AKT1/hsa-miR-125b-1) has the best predictive power in distinguishing metastatic and non-metastatic phenotypes of SKCM tumor samples." (PMID 32703153, 2020).
cancer (261 papers, 2013 to 2026). A tumor composed of atypical neoplastic, often pleomorphic cells that invade other tissues. "LncRNA urothelial carcinoma-associated 1 (UCA1) is one of the cancer-related lncRNAs, initially discovered in 2006 as being overexpressed in bladder cancer cells." (PMID 39937792, 2025). "In hypoxic conditions, the lncRNA urothelial carcinoma-associated 1 (UCA1) was upregulated in cancer cell-derived exosomes and contributed to cancer progression via multiple signaling pathways." (PMID 41551597, 2025). "lncRNA urothelial carcinoma-associated 1 (UCA1) is a well-studied lncRNA known for its involvement in various cancers, including NSCLC." (PMID 39452836, 2024). "It has been established that UCA1 was upregulated in pancreatic cancer tissue, and its overexpression was associated with enhanced migration and invasion of cancer cells and poor prognosis." (PMID 38226210, 2024). "For instance, the urothelial cancer-associated lncRNA 1 (UCA1) plays an important role in the tumorigenesis, progression, and diagnosis of many cancers, mainly bladder cancer." (PMID 35978835, 2022). "In the previous study, the expression of serum UCA1 was suggested to be closely associated with the differentiation of cancer cells in GC." (PMID 35794986, 2022). "Independent evidence suggests that this effect of miR-204-5p is controlled by lncRNA UCA1 (Urothelial Cancer Associated 1), which is oncogenic in many cancers and highly expressed in PTC tissues and cell lines." (PMID 35597813, 2022). "Previous studies have confirmed that lncRNA urothelial carcinoma-associated 1 (UCA1) is abnormally expressed in many cancers and has been confirmed as an oncogene." (PMID 36110528, 2022). "LncRNAs, particularly urothelial carcinoma-associated 1 (UCA1), are oncogenes involved in regulating cancer progression, such as cell proliferation, invasion, migration, and chemoresistance, particularly in GI cancer." (PMID 33936199, 2021). "The lincRNA urothelial cancer-associated 1 (UCA1) is described as an oncogene associated with cancer progression." (PMID 34204634, 2021). "UCA1 expression is significantly upregulated in many types of cancers, and high levels of UCA1 are associated with enhanced cell proliferation, invasion and metastasis." (PMID 34527584, 2021). "Urothelial carcinoma associated 1 (UCA1) is a lncRNA with abnormal expression in a variety of malignant tumors." (PMID 34053467, 2021). "Another study identified 126 lncRNAs including MEG3, ANRIL, and UCA1, which are closely implicated in cancer as putative targets of KSHV miRNA." (PMID 33519750, 2020). "Accumulating studies has pointed out that dysregulation of lncRNAs was associated with various malignant tumors, including urothelial carcinoma associated 1 (UCA1)." (PMID 33204264, 2020). "Among the differentially expressed lncRNAs, the authors identified urothelial cancer associated 1 (UCA1) which has gained much attention in recent years due to its aberrant expression in several cancers." (PMID 32429207, 2020). "Urothelial cancer associated 1 (UCA1) is a novel lncRNA that acts as a potential biomarker and is involved in the development of cancers." (PMID 31996265, 2020). "Urothelial carcinoma associated 1 (UCA1), also known as cancer-resistant drug resistance gene, a 2314-bp lncRNA encoded on human chromosome 19p13.12." (PMID 30918102, 2019). "The long non-coding RNA, urothelial carcinoma associated 1 (UCA1) has been demonstrated to play important roles in various types of cancers." (PMID 31596734, 2019). "The long non-coding RNA (lncRNA) urothelial carcinoma-associated 1 (UCA1) is involved in various cancers and often functions through microRNAs." (PMID 31695578, 2019). "The results of the current study demonstrated that high UCA1 expression level was positively related to increasing the risk of LNM in cancer patients." (PMID 30918102, 2019).